LINC-PINT (long independently transcribed non-coding RNA, p53 induced transcript)
Diseases named in the same sentence as LINC-PINT in open-access papers (continued):
Sharing a sentence is not in itself a finding about the gene and the disease.
acute lymphoblastic leukemia (4 papers, 2018 to 2024). Leukemia with an acute onset, characterized by the presence of lymphoblasts in the bone marrow and the peripheral blood. "In acute lymphoblastic leukemia (ALL), overexpressed linc-PINT decreases cell proliferation via apoptosis activation and cell cycle arrest; however, upregulated NALT promotes cell proliferation through interacting with NOTCH signaling pathway." (PMID 30466456, 2018).
colon cancer (4 papers, 2022 to 2024). "Through analysis of colon cancer data from the TCGA data, we determined an enticing relationship between LINC-PINT expression, prognosis and patients’ survival." (PMID 37006616, 2023). "Other studies have suggested that PUNISHER and LINC-PINT may create a negative feedback regulation loop in colon cancer." (PMID 35670784, 2022).
esophageal cancer (4 papers, 2021 to 2024). A primary or metastatic malignant neoplasm involving the esophagus. "For example, the decreased expression of LINC-PINT has been noticed in esophageal cancer, leading to advanced tumor and node stage and miserable overall survival." (PMID 34257531, 2021). "Besides, miR-576-5p has been reported to be sponged by linc-PINT in esophageal cancer." (PMID 36335356, 2022). "Our research findings revealed a positive correlation between LINC-PINT expression and TMB in several cancer types, including Adrenocortical Carcinoma (ACC), Thymoma (THYM), SKCM, and Esophageal Carcinoma (ESCA) (correlation coefficient > 0, P < 0.05)." (PMID 38553526, 2024).
ovarian carcinoma (4 papers, 2020 to 2024). A malignant neoplasm originating from the surface ovarian epithelium. "For ovarian cancer patients treated with platin, five lncRNAs including LINC01134, HAR1A, LINC01139, LINC-PINT, and DNM3OS were significantly associated with PFS." (PMID 32260415, 2020). "In ovarian cancer, LINC-PINT is downregulated relative to normal ovary cells and tissue samples, whereas miR-21 is upregulated." (PMID 32260415, 2020). "Nasopharyngeal cancer, renal carcinoma, non-small cell lung cancer, glioblastoma, thyroid cancer, retinoblastoma, ovarian cancer, breast cancer, oesophageal squamous cell carcinoma, osteosarcoma, melanoma, and gastric cancer are among those in which LINC-PINT is downregulated." (PMID 40176927, 2024).
cardiomyopathy (3 papers, 2021 to 2022). A disease of the heart muscle or myocardium proper. "This study showed that LINC-PINT is downregulated in patients who develop cardiomyopathy or retinopathy, or both." (PMID 36552599, 2022). "The authors analysed the expression of LINC-PINT in 244 T2D patients with different chronic diabetes-related complications (nephropathy, retinopathy, cardiomyopathy, diabetic foot) and 126 healthy subjects, and in ARPE-19 and AC16 cells." (PMID 34638838, 2021). "Although further confirmations are necessary, these results suggest a role of LINC-PINT in inhibiting the progression of both retinopathy and cardiomyopathy in T2D patients." (PMID 34638838, 2021). "Upregulation of LINC-PINT expression may inhibit the progression of cardiomyopathy and retinopathy in T2DM patients." (PMID 36552599, 2022). "LINC-PINT was downregulated in patients with retinopathy, cardiomyopathy or both." (PMID 34638838, 2021). "Moreover, the overexpression and the silencing of LINC-PINT results in an increase or reduction, respectively, of the viability of HG-treated ARPE-19 and AC16 cells, suggesting that the reduction of LINC-PINT may favor the progression of cardiomyopathy and retinopathy in subjects with T2D." (PMID 36290744, 2022).
Huntington disease (3 papers, 2020 to 2022). Huntington disease (HD) is a rare neurodegenerative disorder of the central nervous system characterized by unwanted choreatic movements, behavioral and psychiatric disturbances and dementia. "In a recent lncRNA screen of brain tissue samples with multiple neurodegenerative conditions, increased expression of LINC-PINT was observed to be associated with Parkinson’s disease (PD), Huntington’s disease (HD) and AD." (PMID 34020725, 2021). "LINC‐PINT also accumulated in several brain regions of Alzheimer's and Huntington's disease patients and decreased with healthy brain aging, suggesting a general role in aging and neurodegeneration for this lncRNA." (PMID 32080970, 2020). "This larger validation cohort revealed consistent elevation in both PD and PD models of NEAT1, which has been implicated in Huntington's disease (HD) and in murine PD models as well as LINC‐PINT, but RMST’s qPCR levels showed no disease‐related changes." (PMID 32080970, 2020).
lung adenocarcinoma (3 papers, 2017 to 2024). A carcinoma that arises from the lung and is characterized by the presence of malignant glandular epithelial cells. "This indicates that the inhibition of EGR1 mediates, at least in part, the less invasive phenotype caused by LINC-PINT in colorectal and lung adenocarcinoma cells." (PMID 29078818, 2017). "We further investigated the phenotype of the enforced expression of LINC-PINT in several cancer cell lines (colorectal HCT116 and DLD1 and lung adenocarcinoma A549)." (PMID 29078818, 2017). "Conversely, in Lung Adenocarcinoma (LUAD), Pancreatic Adenocarcinoma (PAAD), Sarcoma (SARC), and Skin Cutaneous Melanoma (SKCM), LINC-PINT assumed the role of a favorable gene (HR < 1, P < 0.05), thereby demonstrating an encouraging association with improved OS outcomes." (PMID 38553526, 2024).
asthma (2 papers, 2019 to 2025). "LINC-PINT regulates immune responses in asthma by inhibiting abnormal ASMC proliferation via the miR-26a-5p/PTEN pathway, indicating a tumor suppressor-like function." (PMID 40806181, 2025).
bladder cancer (2 papers, 2023 to 2024). "LINC-PINT is a promising prognostic marker for bladder cancer, and its upregulation can suppress the proliferation, invasion, and migration of bladder cancer cells by targeting miR-155-5p." (PMID 38532369, 2024). "In bladder cancer, LINC-PINT could inhibit the proliferation, invasion and migration by targeting miR-155-5p, and it was a potential prognostic marker for bladder cancer." (PMID 37341994, 2023).
brain tumor (2 papers, 2018 to 2019). "Other circRNAs such as circ-FBXW7 and circ-LINC-PINT were reported to be translated in brain tumors, suggesting that additional coding circRNAs have yet to be discovered." (PMID 31861825, 2019). "CircPINTexon2 and PINT87aa were expressed in tumor-adjacent normal brain tissues, but their expression decreased in all brain tumor tissues, similar to LINC-PINT." (PMID 30367041, 2018).
cholangiocarcinoma (2 papers, 2018 to 2024). A carcinoma that arises from the intrahepatic biliary tree (intrahepatic cholangiocarcinoma) or from the junction, or adjacent to the junction, of the right and left hepatic ducts (hilar cholangiocarcinoma). "Remarkably, in stark contrast, we observed a notable upregulation of LINC-PINT in Cholangiocarcinoma (CHOL), Colon Adenocarcinoma (COAD), Liver Hepatocellular Carcinoma (LIHC), Rectum Adenocarcinoma (READ), and Stomach Adenocarcinoma (STAD)." (PMID 38553526, 2024).
colon adenocarcinoma (2 papers, 2023 to 2024). "We further associate LINC-PINT with immune responses in colon adenocarcinoma, proposing the potential utility of LINC-PINT as a novel biomarker of immune checkpoint inhibitors." (PMID 37006616, 2023).
laryngeal carcinoma (2 papers, 2020 to 2022). Carcinoma that arises from the laryngeal epithelium. "It has been found that long noncoding RNA LINC-PINT regulates laryngeal carcinoma cell stemness and chemoresistance by targeting miR-425-5p in laryngeal tumors." (PMID 33123581, 2020). "While LINC‐PINT expression was downregulated in laryngeal carcinoma tissues, it acted as a suppressor through the LINC-PINT/miR-425-5p/PTCH1 axis." (PMID 35568824, 2022).
liver cancer (2 papers, 2023). An epithelial or non-epithelial malignant neoplasm that arises from the liver. "Moreover, two SNPs in LINC-PINT (rs157916 and rs16873842) was associated witn a reduced risk of steroid-induced osteonecrosis of the femoral head, and LINC-PINT polymorphisms (rs157916, rs16873842, and rs7801029) were associated with reduced risk liver cancer." (PMID 37553573, 2023). "For example, in viral hepatitis leading to liver cancer development, LINC-PINT foremost contributes to inflammation during viral infection and then later, to the pathogenic properties of the cancer cells, but whether the underlying processes involved are the same in both disease stages is not clear." (PMID 37006616, 2023).
lung squamous cell carcinoma (2 papers, 2017 to 2024). "This analysis showed that LINC-PINT is significantly decreased in several cancer types including breast, uterine corpus endometrial, and lung squamous cell carcinomas among others." (PMID 29078818, 2017). "The results demonstrated that in certain specific tumor types, such as bladder urothelial carcinoma, breast invasive carcinoma, and lung squamous cell carcinoma, as the tumor stage progressed, there was a notable decrease in LINC-PINT expression." (PMID 38553526, 2024).
non-small cell lung carcinoma (2 papers, 2021 to 2022). A group of at least three distinct histological types of lung cancer, including non-small cell squamous cell carcinoma, adenocarcinoma, and large cell carcinoma. "LINC-PINT overexpression also suppresses the biological performance of non-small cell lung cancer cells such as cell proliferation, migration and invasion, which has been corroborated by in vivo experiments." (PMID 34257531, 2021).
osteosarcoma (2 papers, 2020). A usually aggressive malignant bone-forming mesenchymal neoplasm, predominantly affecting adolescents and young adults. "LncRNA LINC-PINT acted as a tumor suppressor in osteosarcoma through repressing miRNA-21." (PMID 32669970, 2020).
Parkinson's (2 papers, 2020 to 2022). "Recent reports highlight that linc-PINT is a neuronal transcript which is upregulated in several brain regions of patients with Alzheimer's, Parkinson's and Huntington's disease." (PMID 35523833, 2022).
pulmonary edema (2 papers, 2021 to 2023). Accumulation of fluid in the lung tissues causing disturbance of the gas exchange that may lead to respiratory failure. "LINC-PINT polymorphism rs157928 has a significant association with a reduced risk of high-altitude pulmonary edema." (PMID 37553573, 2023). "For instance, rs157928 in LINC-PINT was significantly associated with a decreased risk of high-altitude pulmonary edema." (PMID 37553573, 2023). "Such as polymorphisms of LINC-PINT and LINC00599 are associated with high-altitude pulmonary edema in Chinese populations." (PMID 33934713, 2021).
amyloid (1 paper, 2021). "However we note that the level of CAA in these individuals is very low and postulate that the LINC-PINT variant may not afford discernable protection from vascular amyloid pathology in the absence of ADNC." (PMID 34020725, 2021).
clear cell renal cell carcinoma (1 paper, 2021). "The interaction between LINC-PINT and EZH2 has been mentioned in clear cell renal cell carcinoma (ccRCC)." (PMID 34257531, 2021).
cognitive decline (1 paper, 2020). "Furthermore, web‐available data of transcriptomic patterns in neurodegeneration revealed increases in LINC‐PINT expression in HD and AD, where this increase correlated with cognitive decline but not with the brain's pathological hallmarks, suggesting that it is not merely a marker of tissue damage." (PMID 32080970, 2020).
Cognitive impairment (1 paper, 2020). Abnormal cognition is characterized by deficits in thinking, reasoning, or remembering. "Intriguingly, LINC‐PINT elevation was correlated with increased cognitive impairment but not with exacerbated brain pathology (GSE70424)." (PMID 32080970, 2020).
esophageal squamous cell carcinoma (1 paper, 2021). Esophageal squamous cell carcinoma (ESCC) is a type of esophageal carcinoma (EC) that can affect any part of the esophagus, but is usually located in the upper or middle third. "Moreover, in esophageal squamous cell carcinoma (ESCC), the recurrence of ESCC is connected to downregulated LINC-PINT expression, whose upregulation suppresses the migration and invasiveness of ESCC cells." (PMID 34257531, 2021).
head and neck squamous cell carcinoma (1 paper, 2024). A squamous cell carcinoma that arises from any of the following anatomic sites: lip and oral cavity, nasal cavity, paranasal sinuses, pharynx, larynx, and salivary glands. "Moreover, in Head and Neck Squamous Cell Carcinoma (HNSC), heightened LINC-PINT expression was associated with poorer PFI (P = 0.036)." (PMID 38553526, 2024).
hepatitis C (1 paper, 2022). "In addition, LINC-PINT expression, found to be repressed in hepatocytes of hepatitis C-affected individuals, was responsible for lipogenesis enhancement." (PMID 36430946, 2022).
lymph node metastasis (1 paper, 2021). "The incidence of lymph node metastasis was much higher in patients with lower LINC-PINT expression when compared with those with higher LINC-PINT expression (P < 0.01)." (PMID 34257531, 2021). "The downregulation of LINC-PINT related to dismal prognosis and unfavourable clinicopathological characteristics, including advanced TNM stage, differentiation and lymph node metastasis for LSCC patients." (PMID 34257531, 2021).
malignant glioma (1 paper, 2021). A grade III or grade IV glioma arising from the central nervous system. "For example, circPINT, circulated from lincPINT, could encode a PINT-87aa protein under IRES existence conditions to inhibit the occurrence of malignant glioma." (PMID 33806945, 2021).
mesothelioma (1 paper, 2024). A usually malignant and aggressive neoplasm of the mesothelium which is often associated with exposure to asbestos. "Finally, as for Progression-Free Interval (PFI), LINC-PINT exhibited a beneficial effect (HR < 1, P < 0.05) in Mesothelioma (MESO), PAAD, and SKCM, thus offering potential therapeutic implications in these malignancies." (PMID 38553526, 2024).
myelosuppression (1 paper, 2017). Myelosuppression or bone marrow suppression is a condition in which bone marrow activity is decreased, resulting in fewer red blood cells, white blood cells, and platelets. "The LINC-PINT rs1059698 CC genotype was a protective factor in neutropaenia and myelosuppression." (PMID 28814798, 2017).
nasopharyngeal carcinoma (1 paper, 2021). A carcinoma arising from the nasopharyngeal epithelium. "In this study, LINC-PINT was significantly downregulated in nasopharyngeal cancer tissues than in rhinitis tissues, and low LINC-PINT expressions showed poorer prognosis in patients who received radiotherapy." (PMID 33963177, 2021).
neuroblastoma (1 paper, 2020). Neuroblastoma (NB) is the most common solid, extracranial childhood tumor. "To understand the functional role of LINC‐PINT and thereby distinguish between these options, we used the murine neuroblastoma cell line N2A to model Lncpint knockdown through the use of siRNA pools (siTools) which specifically target it with minimal off‐target effects." (PMID 32080970, 2020). "To test whether this decrease could be mediated by LINC‐PINT, we modeled its neuronal knockdown by administering LINC‐PINT‐targeted GapmeRs (Qiagen) to the human neuroblastoma cell line SH‐SY5Y." (PMID 32080970, 2020).
osteonecrosis of (1 paper, 2023). "For instance, LINC-PINT polymorphisms (rs157916 and rs16873842) are associated with reduced risk of steroid-induced osteonecrosis of the femoral head in the Chinese Han population." (PMID 37553573, 2023).
prostate adenocarcinoma (1 paper, 2024). "Conversely, in COAD, KIRC and Prostate Adenocarcinoma (PRAD), LINC-PINT acted as a detrimental factor (HR > 1, P < 0.05)." (PMID 38553526, 2024).
retinoblastoma (1 paper, 2024). A malignant tumor that originates in the nuclear layer of the retina.
rheumatoid arthritis (1 paper, 2023). A chronic, systemic autoimmune disorder characterized by inflammation in the synovial membranes and articular surfaces. "LINC-PINT is downregulated in rheumatoid arthritis (RA) tissues and TNF-α stimulated RA cells, increasing SOCS1 expression by inhibiting the activation of the ERK signaling pathway in RA synovial fibroblasts induced by TNF-α by sponging miR-155-5p." (PMID 37553573, 2023).
rhinitis (1 paper, 2021). An inflammation of the mucous membrane lining the nose, usually associated with nasal discharge. "Following a receiver-operating characteristic (ROC) curve-based approach, we found the expression level of LINC-PINT could distinguish cancer tissues from rhinitis tissues effectively (AUC = 0.901) based on our data." (PMID 33963177, 2021).
serous ovarian cancer (1 paper, 2020). "For serous ovarian cancer patients treated with platin, five lncRNAs including HAR1A, LINC00886, LINC01139, LINC-PINT, DNM3OS were significantly associated with PFS." (PMID 32260415, 2020). "For serous ovarian cancer patients, three lncRNAs including HAR1A, LINC00886, and LINC-PINT were significantly associated with PFS." (PMID 32260415, 2020).
testicular germ cell tumor (1 paper, 2024). A germ cell tumor arising from the testis. "Conversely, in UCEC, THCA, Testicular Germ Cell Tumors (TGCT), STAD, KIRC, COAD, and BRCA, LINC-PINT expression exhibited a negative correlation with TMB (correlation coefficient < 0, P < 0.05)." (PMID 38553526, 2024).